IL22 (interleukin 22)
Diseases named in the same sentence as IL22 in open-access papers (continued):
Sharing a sentence is not in itself a finding about the gene and the disease.
colitis (continued). "In addition, PMN recruitment has been shown to aggravate experimental colitis; this may occur via the PMN's ability to induce protective responses within IECs via the induction of hypoxia-inducible factor (HIF) or the secretion of interleukin-22 (IL-22)." (PMID 26569316, 2015). "Additionally, studies in genetically engineered mice have demonstrated that epithelial STAT3 activation in dextran sodium sulfate colitis is dependent upon IL-22 rather than IL-6, and that both IL-22 and epithelial STAT3 is important in wound-healing experiments in vivo." (PMID 23379788, 2013). "The mechanism for this resistance to colitis may be attributable to increased IL-22/JAK2/STAT3 signaling, since recent studies indicate that activation of STAT3 within the intestinal epithelium plays an important role in mucosal tissue repair through secretion of IL-22 from innate immune cells." (PMID 22675454, 2012). "In sum, liraglutide was shown to promote IL-22 production by ILC3 without increasing proinflammatory cytokines, leading to improved inflammation in the DSS-induced colitis model." (PMID 40426955, 2025). "Specific deletion of SIRT6 in ILC3s enhances IL-22 production without affecting the number of ILC3s, thus resulting in enhanced protection of DSS-induced colitis." (PMID 41194916, 2025). "In PBS-treated males, colitis resulted in markedly elevated IL-6 and no significant changes in PST, IL-22, and IL-18 levels compared to in the corresponding non-colitic PBS-treated mice." (PMID 39684467, 2024). "DR3-driven loss of ILC3s in the large intestine is an essential factor contributing to the exacerbation of colitis, and mice lacking CD93 expression in ILC3s also exhibit impaired IL-22 production and increased colonic inflammation." (PMID 39162488, 2024). "Although DSS-administered ERdj5-KO mice treated with UDCA had restored IL-22 levels, we believe that this UDCA-driven amelioration of DSS-induced colitis in ERdj5-KO mice was independent of the restoration of IL-22 levels." (PMID 36759578, 2023). "Our own work showed for the first time that exuberant production of IL-22 by GALT cells in the absence of a transcription suppressor, MSC, aggravates colitis even in the acute DSS model." (PMID 34992594, 2021). "Interestingly, IL-23 could also act via intestinal epithelial cells, inducing the c-type lectin RegIIIβ-mediated recruitment of IL-22-producing cells, and in the absence of this signaling (Il23rflox/floxVillin-Cre), mice were susceptible to DSS colitis and were characterized by dysbiosis." (PMID 33562334, 2021). "Ameliorated colitis through AhR signaling activation, increased the expression of anti-inflammatory cytokines, and resulted in the expansion of IL-10-producing CD4+ T cells and IL-22-producing CD3−RORγt+ cells, but not CD4+Foxp3+ regulatory T cells." (PMID 40756994, 2025). "Although there is no direct evidence that TFAM regulates IL-22, the lack of mitochondrial-derived energy by insufficient TFAM could limit the activation of ILC3s and effector cytokine secretion in colitis." (PMID 39103576, 2024). "In addition, the anti-inflammatory cytokines, IL-10 and IL-22, are also increased in DSS- induced colitis, suggesting that negative feedback is activated to limit the progress of inflammation." (PMID 35933374, 2022). "Detection of the microbial metabolites, short chain fatty acids (SCFA), by ILC3 is important for IL-22 production and promoting epithelial barrier function as, in DSS colitis, ILC3 lacking Ffar2 – a receptor for SCFA, display reduced proliferation and impaired IL-22 production." (PMID 33936115, 2021). "However, lack of IL-22 and impaired ILC3 function has been shown to aggravate experimental colitis and various microbial infections due to their role in barrier function maintenance and intestinal homeostasis (reviewed in Zhou and Sonnenberg)." (PMID 34118489, 2021).
colitis (continued). "In TNBS-induced colitis in humanized mice, the nontoxic AHR agonist methyl 2-(1’H-indole-3’-carbonyl)-thiazole-4-carboxylate (ITE) induced functional human Tregs, which inhibited effector T-cell proliferation in vitro in a CD39- and granzyme B-dependent manner, leading to the up-regulation of IL-22." (PMID 41019044, 2025). "To confirm the hypothesis that IFN-I contributes to ileal inflammation in Atg16l1ΔIEC mice independent of an exogenous IL-22 stimulus, we performed a 2% DSS colitis with either anti-IFNAR or with corresponding IgG control at days 0, 2, 4, and 6 in the without IL-22 injection." (PMID 30254094, 2018).
inflammatory bowel disease (124 papers, 2010 to 2026). A spectrum of small and large bowel inflammatory diseases of unknown etiology. "In inflammatory bowel disease, highly pathogenic Th17 cells expand and secrete proinflammatory cytokines, such as IL-17A and IL-22, which can cause a wide range of inflammatory responses." (PMID 33553436, 2021). "Many components in the IL-22-pSTAT3 pathway have been identified as risk factors for inflammatory bowel disease (IBD) and some of them are considered as promising therapeutic targets." (PMID 30455690, 2018). "IL-22 also prevents inflammatory bowel disease (IBD) by producing a pancreatitis-associated protein in pancreatic acinar cells, and can prevent autoimmune liver diseases, such as primary biliary cirrhosis (PBC)." (PMID 29679037, 2018). "IL-22 is highly expressed by Th17 cells and is tightly linked to chronic inflammation, including inflammatory bowel disease and local intestinal inflammation among others." (PMID 24623532, 2014). "Research indicates that IL-22 expression is intricately linked to the diversity of intestinal microbiota, with IL-22 deficiency potentially resulting in dysregulation of the intestinal microbiota and contributing to conditions such as inflammatory bowel disease." (PMID 41019044, 2025). "On the other hand, the overexpression of IL-22 is associated with hyper-proliferation and recruitment of pathologic effector cells, leading to tissue damage and chronic inflammation in specific diseases including inflammatory bowel disease (IBD)." (PMID 39354587, 2024). "Most IL-22-related molecules are encoded by inflammatory bowel disease (IBD) susceptibility genes and play a central role in host resistance to intestinal inflammatory injury by maintaining the integrity of the epithelial barrier and inducing the production of antimicrobial peptides (AMPs)." (PMID 38169949, 2023). "IL-26 is associated with the activation of Th17 and CD4+ IL-22+ T-cells; it also plays a role in inflammatory bowel disease, which may associate with the extra-pulmonary gastroenteritis manifestation during SMPP." (PMID 36618370, 2022). "The theory that exuberant production of IL-22 under pathological conditions (e.g., in human inflammatory bowel disease, IBD) may cause epithelial inflammation due to endoplasmic reticulum (ER) stress response is worth further investigation." (PMID 34992594, 2021). "Targeting of IL-22 may have therapeutic potential for treatment of diseases in which the IL-22 signaling pathway is implicated including inflammatory bowel disease, inflammatory skin disorders or multiple sclerosis." (PMID 30619294, 2018). "Additionally, there are multiple T cells producing IL-22 in fibrotic skin tissue in cases of scleroderma, whereas there is a decrease in these cells at lesion sites associated with inflammatory bowel disease." (PMID 30619268, 2018). "In Inflammatory Bowel Disease (IBD), patients with Crohn's disease have a loss of colonic or ileum IL-22-producing ILCs (including ILC3s) and an increase in IFNγ/IL-17A-producing ILCs." (PMID 30984202, 2019). "In humans, however, the core function of IL-22 shifts to immune regulation, participating in the maintenance of intestinal immune homeostasis, and is closely related to the pathogenesis of inflammatory bowel disease, such as Crohn disease." (PMID 41300695, 2025). "For instance, a sequential treatment involving probiotics, a Mediterranean diet, and FMT activates the Akkermansia-mediated IL-22/REG3γ pathway, leading to substantial synergistic effects in promoting mucosal healing in models of inflammatory bowel disease." (PMID 40661744, 2025). "Ganoderic Acid A (GAA) can potentially ameliorate inflammatory bowel disease by modulating the intestinal flora and enhancing AhR activity, which in turn promotes IL-22 production and improves intestinal barrier function." (PMID 41019044, 2025).
inflammatory bowel disease (continued). "Phosphorylated STAT3 then dimerizes, translocates, and binds to DNA, resulting in the production and release of inflammatory factors IL-17, IL-21, and IL-22, collectively influencing inflammatory bowel diseases like UC." (PMID 40446056, 2025). "Our finding provided insight into the relation of epigenetic regulators with IL-22 production and supplied a new perspective for a potential strategy against inflammatory bowel disease." (PMID 39253083, 2024). "This is supported by IL-22 ablation decreasing ER stress-related transcripts and improving histological disease scores in a microbiota-induced mouse model of inflammatory bowel disease." (PMID 38551817, 2024). "A study on patients with inflammatory bowel disease found that SCFAs, metabolites of gut microbiota, in particular propionate, regulate IL-17 and IL-22 production by human intestinal γδ T lymphocytes by inhibiting HDAC activity." (PMID 38915127, 2024). "Studies using genetic mouse models have shown that MSC deficiency leads to spontaneous gut and lung inflammation with age34 while also enhancing inflammation and IL-22 secretion in inflammatory bowel disease models." (PMID 37012418, 2023). "Previous study has demonstrated that CD177+ neutrophils play a protective role in the pathogenesis of inflammatory bowel diseases (IBD) through increased IL-22 production and bactericidal activity." (PMID 36729914, 2023). "On the other hand, anti-inflammatory effects of IL-22 have been identified in other inflammatory conditions such as inflammatory bowel disease." (PMID 36875710, 2023). "Although IL-22 has an anti-inflammatory role in inflammatory bowel diseases, it can promote inflammatory conditions in autoimmune diseases such as rheumatoid arthritis (RA), Crohn’s disease, and various skin diseases." (PMID 35054942, 2022). "ILC1 innate lymphoid cells were demonstrated to hold a crucial role in the IL22 production and, thus, regulation of inflammatory bowel disease, but are markedly distinct from conventional natural killer (NK) cells." (PMID 35328501, 2022). "The role of the IL-22 in tissue repair has been recently reported, particularly in mucosal healing in inflammatory bowel disease." (PMID 35409053, 2022). "IL-22 is upregulated in inflammatory bowel diseases (IBD) as Crohn's disease but also in coeliac disease." (PMID 33912578, 2021). "Importantly, IL-22-secreting ILC3 have been implicated in the control of inflammatory bowel disease (IBD) and were shown to reduce the incidence of graft-versus-host disease (GvHD) as well as the risk of transplant rejection." (PMID 35003122, 2021). "For example, mutations in gene ATG16L1 promote the production of IL-22 in the intestinal epithelium through cGAS/STING pathway, which result in excessive epithelial cell death and inflammatory bowel disease (IBD)." (PMID 35006429, 2020). "This can be attributed to the compensatory effect of IL-22, which has been shown in inflammatory bowel disease and ulcerative colitis." (PMID 31214623, 2019). "IL-22+ILC3s limit inflammatory colitis, and their frequency correlates with mucosal repair in inflammatory bowel disease (IBD)." (PMID 32117199, 2019). "In contrast, IL-22 represents an inducible cytokine in the large intestine where IL-22 expression is hardly detectable under healthy state and can be induced under inflammatory conditions such as inflammatory bowel disease (IBD)." (PMID 29075900, 2018). "Most importantly, clinical relevance of IL-22 to inflammatory bowel disease has been well highlighted." (PMID 29075900, 2018). "In a recent landmark paper, IL-22 was shown to have regulatory properties in inflammatory bowel disease." (PMID 29163483, 2017). "IL-22 is a member of the IL-10 family of cytokines, which exerts an anti-inflammatory role in hepatitis and inflammatory bowel disease and plays an important role in host defence against infectious diseases, especially those caused by extracellular pathogens." (PMID 28969688, 2017).
inflammatory bowel disease (continued). "More recently, anti-TNF therapy has been shown to be effective in inflammatory bowel disease in part through suppressing IL-22-binding protein thereby implicating IL-22 as a protective cytokine." (PMID 29163483, 2017). "As an unusual interleukin that induces the production of antibacterial proteins and specific chemokines, IL-22 has been shown to ameliorate pancreatitis, hepatitis, inflammatory bowel disease, ulcerative colitis and diabetic wounds." (PMID 26784895, 2016). "It is interesting to note that ceruloplasmin recently has been shown to be protective in mouse models of inflammatory bowel disease, where IL-22 has also been shown to be protective." (PMID 24498387, 2014). "IL-22 has been shown to be an important mediator in dermal inflammation, and has protected mice from inflammatory bowel disease (IBD)." (PMID 24623532, 2014). "Th17 cells are a subset of CD4+ T cells that can secrete IL-17, IL-22, IL-6, and TNF-α, and have been implicated in autoimmune diseases, including multiple sclerosis, lupus, inflammatory bowel disease, RA, IDDM, and experimental autoimmune encephalomyelitis." (PMID 24586733, 2014). "Evidence has shown that IL-22 contributed to regulating hepatitis and is protective in inflammatory bowel disease." (PMID 22312190, 2012). "Studies have revealed that cytokines such as RORγt, IL-17A, and IL-21 expressed in the mucosa not only contribute to inflammatory bowel disease but also lead to elevated mRNA levels of IL-17A, IL-22, and TNF-α in knee joint tissues, which was observed in mouse models of rheumatoid arthritis." (PMID 41400824, 2026). "Studies have also found that in the context of chronic inflammation or inflammatory bowel diseases (such as Crohn’s disease and ulcerative colitis), ILC3s may continuously secrete IL-22 to try to balance ongoing tissue damage and repair needs." (PMID 40006939, 2025). "Furthermore, IL-22 is also demonstrated for protective functions in several diseases such as asthma, inflammatory bowel disease (IBD), and hepatitis." (PMID 39354587, 2024). "However, some studies have shown that ILCs can respond to IL-23-mediated inflammatory bowel disease (IBD) by producing IL-22 and IL-17." (PMID 38384457, 2024). "Importantly, IL22 is involved in epithelial homoeostasis, in particular intestinal permeability, and is up-regulated in inflammatory bowel disease (IBD)." (PMID 38071324, 2023). "Moreover, the role of IL-22 in intestinal wound repair can be deducted from its important role in regeneration in inflammatory bowel diseases." (PMID 35409053, 2022). "Nonetheless, IL-22 has an anti-inflammatory effect on inflammatory bowel diseases." (PMID 35054942, 2022). "Subsequently, inhibition of IL-22 may be beneficial in cancer, whereas an enhanced IL-22 expression may be favorable in gut infections and inflammatory bowel disease." (PMID 35295139, 2021). "Interleukin-22 (IL-22) plays a role in epithelial barrier function and repair, and may provide benefits in conditions like inflammatory bowel disease." (PMID 34360971, 2021). "Interleukin-22 (IL-22) has been shown to promote mucosal healing, and to repair epithelial tissue in mouse models, highlighting its potential as a therapeutic agent for diseases with compromised barrier function, including inflammatory bowel disease (IBD)." (PMID 34360971, 2021). "Early studies found IL-22 upregulation in many inflammatory conditions such as rheumatoid arthritis, psoriasis, inflammatory bowel disease, asthma, and hyperIgE/STAT3 mutation, suggesting promotion of pro-inflammatory pathways." (PMID 32637365, 2020). "While IL-22 is a potent inflammatory mediator, it may exert a protective influence in both clinical and experimental inflammatory bowel disease." (PMID 28584821, 2017). "IL-22 provides protection against hepatitis and inflammatory bowel disease (IBD)." (PMID 29048384, 2017).